NOD2 (nucleotide binding oligomerization domain containing 2)
Diseases named in the same sentence as NOD2 in open-access papers (continued):
Sharing a sentence is not in itself a finding about the gene and the disease.
melanoma (continued). "Overexpression of NOD2 in melanoma inhibited cell proliferative viability, colony-forming ability, and DNA synthesis rate, whereas the opposite effect was observed with NOD2 knockdown." (PMID 39353904, 2024). "To understand the role of NOD2 in melanoma, we identified TYMS as a critical gene regulated by NOD2." (PMID 39353904, 2024). "Although NOD2 exhibits biological functions and therapeutic potential in various diseases, its specific role and mechanism in melanoma require further investigation." (PMID 39353904, 2024). "The upregulation of NOD2 inhibited melanoma cell proliferation and migratory invasion while promoting apoptosis." (PMID 39353904, 2024). "All of the data obtained further highlight the critical role of NOD2 in inhibiting the proliferation of human melanoma cells." (PMID 39353904, 2024). "Instead, we found a significant increase in NK cells in metastatic melanoma colonies after NOD2-dependent LY6Clo I-NCMs were adoptively transferred into Nod2–/– mice or after MDP treatment of Nr4a1–/– mice." (PMID 39545417, 2024). "In summary, combination therapy for melanoma cell progression is an effective therapeutic strategy that can enhance the therapeutic effect by targeting NOD2, TYMS, and PLK1." (PMID 39353904, 2024). "To verify if targeting NOD2 inhibited melanoma development in vivo, we implanted A875 cells with NOD2 overexpression, knockdown, and its control group subcutaneously in nude mice to observe tumor formation." (PMID 39353904, 2024). "To investigate the biological function and mechanism of action of NOD2 in melanoma, we performed transcriptome sequencing of NOD2 overexpressing SK-MEL-110 melanoma cells." (PMID 39353904, 2024). "NOD2 was found to be dysregulated in melanoma and high expression of NOD2 predicts a better prognosis for melanoma patients, which is consistent with the KM survival curve." (PMID 37950289, 2023). "NOD2 acts by regulating the TYMS/PLK1 signaling axis in melanoma." (PMID 39353904, 2024). "We elucidated the role of NOD2 in inhibiting melanoma progression and reducing chemoresistance." (PMID 39353904, 2024). "Moreover, activation of NOD2 combined with 5-FU or CAP synergistically inhibits melanoma proliferation and migration in vitro." (PMID 39353904, 2024). "NOD2 may affect the biological behavior of melanoma cells by regulating the expression and activation status of TYMS and PLK1." (PMID 39353904, 2024). "We studied the influence of NOD2 on the migration and invasion ability in human melanoma cells." (PMID 39353904, 2024). "We verified the anti-tumor effects of NOD2 in melanoma cells." (PMID 39353904, 2024). "The results of real-time PCR and Western blot for mRNA and protein expression levels of cell cycle-related factors showed that in melanoma cells with NOD2 overexpression, Cyclin E1/D1 and CDK2/4 expression levels were downregulated while promoting P27 expression." (PMID 39353904, 2024). "We have validated the tumor suppressor effect of NOD2 in melanoma." (PMID 39353904, 2024). "We further explored the mechanism of NOD2 role in melanoma cell proliferation." (PMID 39353904, 2024). "NOD2 suppresses melanoma development by inhibiting the TYMS/PLK1 signaling axis." (PMID 39353904, 2024). "In this work, we observed that NOD2 expression was decreased in melanoma cells." (PMID 39353904, 2024). "We hypothesized that NOD2 may influence chemoresistance in melanoma through the TYMS/PLK1 signaling axis." (PMID 39353904, 2024). "Since PLK1 is a direct cell cycle checkpoint, we hypothesized that the regulation of melanoma cell behavior by NOD2 depends on changes in PLK1." (PMID 39353904, 2024). "Moreover, NOD2 upregulation reduced chemoresistance, enhancing its effectiveness in combating melanoma cells." (PMID 39353904, 2024). "There is an opposite trend in NOD2 knockdown melanoma cells." (PMID 39353904, 2024).
melanoma (continued). "NOD2 overexpression combined with CQ reduced the proliferation and migration of cells to a greater extent, inhibiting melanoma cell progression." (PMID 39353904, 2024). "The GEPIA and TCGA databases were used to analyze the role of NOD2 in the development of melanoma, and it was found that the expression of NOD2 was significantly downregulated in melanoma compared to normal tissue, especially in metastatic melanoma patients with lower expression levels." (PMID 39353904, 2024). "Several polymorphisms of NOD2 are known; some are recognized to be related to increased cancer risk, nevertheless melanoma appears to not be significantly related to NOD2 polymorphisms." (PMID 35205739, 2022). "The present study suggests for the first time that NOD2 expression levels may be indeed related to melanoma onset." (PMID 35205739, 2022). "Moreover, low expression of NOD2 predicts a poor prognosis in melanoma patients." (PMID 39353904, 2024). "NOD2 may function in melanoma by regulating the expression and activities of TYMS and PLK1." (PMID 39353904, 2024). "In addition to the possible diagnostic role reported in the previous figures, such data indicate that NOD2 and IL-18 expression levels may also have a prognostic value in melanoma." (PMID 35205739, 2022). "NOD2 inhibits thymidylate synthase (TYMS) expression by promoting K48-type ubiquitination modification of TYMS, thereby decreasing the resistance of melanoma cells to 5-fluorouracil (5-FU) and capecitabine (CAP)." (PMID 39353904, 2024). "Then, we examined NOD2 expression in Human Epidermal Melanocytes (HEM) and four melanoma cell lines." (PMID 39353904, 2024). "Overall, our research highlights the protective role of NOD2 in melanoma and suggests that targeting NOD2 and the TYMS/PLK1 signaling axis is a high-profile therapy that could be a prospect for melanoma treatment." (PMID 39353904, 2024). "Furthermore, NOD2 overexpression in combination with TYMS inhibition and combination therapy targeting TYMS and PLK1 showed synergistic inhibition of melanoma proliferation and migration." (PMID 39353904, 2024). "Our results indicate that overexpression of NOD2 could reduce the TYMS level and thus inhibit melanoma cell resistance to chemotherapeutic drugs." (PMID 39353904, 2024). "Also, the significance of implementing NOD2 and the TYMS/PLK1 signaling axis was evaluated as targets for therapeutic intervention in melanoma." (PMID 39353904, 2024). "Employing autophagy inhibitors or NOD2 overexpression in conjunction with autophagy inhibitors effectively curtailed melanoma progression, potentially serving as a mechanism by which TYMS and PLK1 influence melanoma." (PMID 39353904, 2024). "Expression levels of NOD2, BAX, IL-18 and ADRB2 were found to be significantly different in melanoma vs. controls and discriminate melanoma from controls in an extremely effective way, either as single molecules (AUC > 0.93 in all cases) or as a profile, according to the PCA analysis." (PMID 35205739, 2022). "Data reported in the present study support the hypothesis of a beneficial autoimmunity mediated by NOD2, IL-18 and ADRB2, since their expression is shown to be almost abolished in melanoma patients." (PMID 35205739, 2022). "Cluster 3 had high expression of these genes, such as NOD2 and IL18, and high PScore, but according to survival analysis, this model based on metastatic melanoma patients may not be suitable for primary melanoma patients." (PMID 38229080, 2024).
rheumatoid arthritis (11 papers, 2009 to 2025). A chronic, systemic autoimmune disorder characterized by inflammation in the synovial membranes and articular surfaces. "We present a case of a 63-year-old female with common variable immunodeficiency, eosinophilic asthma, and rheumatoid arthritis who was found to have a NOD2 mutation on genetic testing." (PMID 37288206, 2023). "NOD2 is involved in recognizing certain bacteria and stimulating the immune system to respond appropriatelyto reduce the risk of bacterial infections It has been reported that NOD2 expression is increased in areas of inflammation in rheumatoid arthritis and atherosclerosis." (PMID 35764993, 2022). "As a newly identified lncRNA, lncRNA intersectin 1-2 (lnc-ITSN1-2) may induce inflammation in the fibroblast-like synoviocytes (FLS) of rheumatoid arthritis (RA) through promoting the nucleotide-binding oligomerization domain 2 (NOD2)/receptor-interacting protein 2 (RIP2) axis." (PMID 34406596, 2021). "Long non-coding RNA ITSN1-2(lncRNA ITSN1-2) promotes fibroblast-like synovicytes (FLS) proliferation and suppress apoptosis through activation of the NOD2/RIP2 signaling pathway, thereby exacerbating synovitis in Rheumatoid arthritis (RA) pathology." (PMID 40629453, 2025). "In our analysis, the top five enriched pathways were rheumatoid arthritis, pertussis, TNF signaling pathway, IL-17 pathway, and NOD-like receptor signaling pathway, which is consistent with the observation the NOD2-related pathways were involved in the pathogenesis mechanism underlying IBD." (PMID 34211502, 2021). "Similar to stromal cells of the oral mucosa, no basal expression of NOD2 is detectable in Rheumatoid Arthritis Synovial Fibroblasts (RASFs), with NOD2 mRNA expression in these stromal populations only detectable after stimulation with POLYI:C, LPS, or TNFα." (PMID 24137162, 2013). "Synovial tissues were collected from 24 rheumatoid arthritis (RA) patients and 20 osteoarthritis (OA) patients to observe the lncRNA ITSN1-2/NOD2/RIP2 signal in RA synovial tissue and its correlation with RA inflammation and bone destruction." (PMID 40629453, 2025).
atherosclerosis (10 papers, 2012 to 2025). A disease characterized by the build-up of fatty material and calcium deposition in the arterial wall resulting in partial or complete occlusion of the arterial lumen. "Following antibiotic pretreatment, NOD2 stimulation in addition to an oral gavage with the periodontal pathogen Porphyromonas gingivalis decreased atherosclerosis in Apoe-deficient mice, whereas P. gingivalis alone increased atherosclerosis in Nod2/Apoe-deficient mice." (PMID 32588196, 2020). "Hence, in the present study we investigated hypercholesterolemic mice deficient for Nod1 as well as for Nod2 in regard to experimental atherosclerosis, lipid metabolism, insulin resistance and gut microbiota composition." (PMID 32588196, 2020). "Murine Nod2 and MDP treatment promoted the formation of necrotic zones in a murine model of atherosclerosis however, so the relationship between NOD2 and necrosis seems complex." (PMID 35418999, 2022). "Other CpGs in the genes NOD2 and TCP11L1 have been linked to atherosclerosis, and in the TSNARE1 gene, with CRP." (PMID 31212707, 2019). "Our results indicate NOD2-mediated innate immune signaling pathway probably get involved in atherosclerosis formation by stimulating VSMC to produce some inflammatory cytokines." (PMID 22997500, 2012). "Conversely, other studies have suggested that NOD2 and TLR3 have protective functions in vascular diseases, including atherosclerosis; indeed, we previously demonstrated such a function of NOD2 in arterial VSMCs." (PMID 29560100, 2018).
atopic dermatitis (10 papers, 2007 to 2025). "Though NOD1/2 signaling is typically associated with pathogen recognition and innate immune responses, genetic variants in NOD1 and NOD2 have been associated with atopic dermatitis 58–60, suggesting a role in allergic inflammation." (PMID 40470207, 2025). "Functional deficiencies in NOD2 might result in a higher risk of S. aureus colonization, often observed in atopic dermatitis." (PMID 33925158, 2021). "NOD2 polymorphisms have also been associated with a variety of human inflammatory diseases, such as atopic eczema, arthritis, atopic dermatitis, sarcoidosis, and possibly asthma, and endometrial or prostate cancer." (PMID 23162548, 2012). "In atopic dermatitis cohorts NOD1 SNPs were associated with increased IgE levels, and more weakly with atopic dermatitis, while a polymorphic NOD2 allele was associated with an almost 2-fold risk of atopic dermatitis." (PMID 33925158, 2021). "Genetic variants for both NOD1 and NOD2 (and also NLRP12) are linked to atopic dermatitis." (PMID 33925158, 2021). "Human data show S. aureus-induced activation of NOD2 in keratinocytes results in increased expression of IL-17C, a pathway that might be dysregulated in atopic dermatitis." (PMID 33925158, 2021). "Furthermore, a missense variant of NOD2 and a rare NOD1 haplotype were observed more frequently in patients with atopic dermatitis than in control subjects." (PMID 33925158, 2021).
autoimmune disease (9 papers, 2009 to 2023). A disorder resulting from loss of function or tissue destruction of an organ or multiple organs, arising from humoral or cellular immune responses of the individual to their own tissue constituents. "In fact, mutations that affect NOD2 expression or activity have been associated with multiple chronic inflammatory and autoimmune diseases." (PMID 29616010, 2018). "Most genes were related to autoimmune diseases like ATM, NCF1, MCM4, FCN3, and DOCK8 or autoinflammatory diseases associated with the release of IFN-gamma, such as PRF1, NOD2, and MEF." (PMID 37588055, 2023). "The gene networks identified contain hallmark genes for each category, for example, PTPN22 and MHC genes for polygenic autoimmune diseases and NOD2 for polygenic autoinflammatory diseases." (PMID 27964755, 2016). "In fact, in animal models, NOD2-agonistic MDP induces autoimmune diseases such as experimental encephalomyelitis, orchitis, uveoretinitis, thyroiditis, and polyarthritis." (PMID 19594951, 2009). "CAT predicts that the original mice will not experience either autoimmune disease or chronic inflammation whereas the third mouse will develop experimental autoimmune myocarditis and develop chronic inflammation driven specifically by TLR2, 4 and 7 and NOD2." (PMID 32629865, 2020).
familial Mediterranean fever (9 papers, 2008 to 2025). Familial Mediterranean fever (FMF) is an autoinflammatory disorder characterized by recurrent short episodes of fever and serositis resulting in pain in the abdomen, chest, joints and muscles. "8/46 patients who had prominent fevers and/or systemic inflammation had testing for monogenic autoinflammation: mevalonate kinase deficiency (7/8), cryopyrin-associated periodic fever (4/8), familial Mediterranean fever (8/8) and NOD2 (1/8) mutations." (PMID 26833394, 2016). "Genetic testing for gene mutations of NOD2, tumor necrosis factor receptor-associated periodic fever syndrome (TRAPS) and familial Mediterranean fever (FMF) was performed." (PMID 21914217, 2011).
Autoimmunity (8 papers, 2009 to 2026). The occurrence of an immune reaction against the organism's own cells or tissues. "For example, common IRF5 polymorphisms contribute to the individual variability in the magnitude of cytokine production induced by the NOD2 and TLR ligands in human monocyte-derived DCs, and IRF5 alleles associated with autoimmunity lead to increased cytokine secretion." (PMID 36677464, 2023). "NOD2 is an intracellular sensor for small peptides, plays key roles in innate immune responses and also cross-talks with TLRs to participate in the development of autoimmunity." (PMID 36560538, 2022). "Similarly, other genes including NOD2 and FOXP3 are regarded as master switches of autoimmunity, and these genes were not included in this study." (PMID 19180256, 2009).
autoinflammatory syndrome (8 papers, 2018 to 2025). A group of disorders of the innate immune system characterized by attacks of seemingly unprovoked inflammation without significant levels of either autoantibodies or autoreactive T cells more characteristic of autoimmune disease. "Future work should catalogue similar cases of compound heterozygous mutations of MEFV and NOD2/CARD15 to define the influence of genetic variation on disease presentation of autoinflammatory syndromes." (PMID 35591901, 2022). "This case identifies novel heterozygous variants in the MEFV and NOD2 genes that might have pathogenic significance in autoinflammatory syndromes." (PMID 35591901, 2022). "In this context, the presence of heterozygous variants in the NOD2 and NLRP12 genes, documented in our patient is also noteworthy, as both have been linked to autoinflammatory syndromes with myalgia and intestinal inflammation." (PMID 41488909, 2025). "In a previous study, using a next generation sequencing approach, we found many rare variants and some functional polymorphisms in genes related to autoinflammatory syndromes (AID): CECR1, MEFV, MVK, NLRP3, NOD2, PSTPIP1 and TNFRSF1A in our BD cohort." (PMID 30808881, 2019). "We describe a case of an autoinflammatory syndrome with a FMF-like presentation characterized by recurrent fevers, colchicine resistance, tocilizumab sensitivity and novel compound heterozygous mutations in the MEFV and NOD2 genes." (PMID 35591901, 2022).
Hyperglycemia (8 papers, 2017 to 2025). An increased concentration of glucose in the blood. "A reduction in NOD2 in L-cells during hyperglycemia may explain the loss of effect of MDP on GLP-1 in the obese mice." (PMID 32722085, 2020). "A previous study showed that NOD2 was upregulated in diabetic patient biopsies, and NOD2 knockout alleviated the hyperglycemia-induced nephrin expression reduction in diabetic mice." (PMID 35387335, 2022). "Glucose may also activate NOD2 during hyperglycemia-induced podocyte dysfunction observed in diabetic nephropathy." (PMID 33503814, 2021). "Our data suggest that AS-IV may ameliorate hyperglycemia and inhibit the NOD2-related NF-κB signaling, which crosstalks with the MAPK signaling, attenuating inflammation in DN rats." (PMID 32855769, 2020). "Among numerous NLRs, The classic antimicrobic receptor nucleotide-binding oligomerization domain containing protein 2 (NOD2) showed enhanced pro-inflammatory effects with PR3-ANCA in vitro, and has been reported to mediate the hyperglycemia-induced podocyte dysfunction in diabetic nephropathy." (PMID 31186034, 2019).
Parkinson disease (8 papers, 2013 to 2024). A progressive degenerative disorder of the central nervous system characterized by loss of dopamine producing neurons in the substantia nigra and the presence of Lewy bodies in the substantia nigra and locus coeruleus. "Further studies required to verify the association between P268S and susceptibility to sporadic Parkinson’s disease in large sample size, and explore the NOD2 functions involved in neurodegenerative diseases." (PMID 23651603, 2013). "Our results suggested that the P268S variant in NOD2 might be a risk factor for susceptibility to sporadic Parkinson’s disease in Chinese populations." (PMID 23651603, 2013). "Two significant gene clusters (clusters 7 and 73) included genes previously associated with Parkinsonism (FIG4 and VAC14) and IBD (IFNAR1, IL6ST, ATG16L1, and NOD2)." (PMID 38741190, 2024).